INHA (inhibin subunit alpha)
Description:
Inhibins and activins inhibit and activate, respectively, the secretion of follitropin by the pituitary gland. Inhibins/activins are involved in regulating a number of diverse functions such as hypothalamic and pituitary hormone secretion, gonadal hormone secretion, germ cell development and maturation, erythroid differentiation, insulin secretion, nerve cell survival, embryonic axial development or bone growth, depending on their subunit composition. Inhibins appear to oppose the functions of activins. Inhibin A is a dimer of alpha/INHA and beta-A/INHBA that functions as a feedback regulator in the hypothalamic-pituitary-gonadal (HPG) axis. Inhibits the secretion of FSH from the anterior pituitary gland by acting on pituitary gonadotrope cells. Antagonizes activin A by binding to the proteoglycan, betaglycan, and forming a stable complex with and, thereby, sequestering type II activin receptors while excluding type I receptor. Inhibin B is a dimer of alpha and beta-B that plays a crucial role in the regulation of the reproductive system by inhibiting the secretion of follicle-stimulating hormone (FSH) from the anterior pituitary gland. Thereby, maintains reproductive homeostasis in both males and females. Acts as a more potent suppressor of FSH release than inhibin A (By similarity). Functions as competitive receptor antagonist binding activin type II receptors with high affinity in the presence of the TGF-beta type III coreceptor/TGFBR3L.
Tractability: Antibody: its Gene Ontology location is reachable by antibodies, with high confidence; UniProt places it where antibodies can reach, with medium confidence; UniProt predicts a signal peptide or a membrane-spanning region. PROTAC: a small molecule that binds it is known.
Gene: Protein-coding gene on chromosome 2 (219,569,162 to 219,575,711, forward strand). Ensembl gene ENSG00000123999.
Subcellular location: Secreted
Subcellular location (Human Protein Atlas): Vesicles; Golgi apparatus; Predicted to be secreted
Pathways (Reactome):
Signal Transduction: Signaling by Activin; Signaling by BMP; TGFBR3 regulates activin signaling
Metabolism of proteins: Glycoprotein hormones
Gene Ontology:
Molecular function: protein binding; protein sequestering activity; signaling receptor binding; cytokine activity; growth factor activity; hormone activity; inhibin binding; protein-containing complex binding
Biological process: hemoglobin biosynthetic process; negative regulation of activin receptor signaling pathway; regulation of cell cycle; regulation of cell population proliferation; cell differentiation; cell surface receptor protein serine/threonine kinase signaling pathway; cell surface receptor signaling pathway; cell-cell signaling; erythrocyte differentiation; negative regulation of B cell differentiation; negative regulation of cell cycle; negative regulation of follicle-stimulating hormone secretion; negative regulation of macrophage differentiation; negative regulation of phosphorylation; negative regulation of type II interferon production; ovarian follicle development; positive regulation of follicle-stimulating hormone secretion; signal transduction; skeletal system development; male gonad development; negative regulation of cell communication; negative regulation of multicellular organismal process; negative regulation of signaling; regulation of follicle-stimulating hormone secretion; system development
Cellular component: inhibin A complex; inhibin-betaglycan-ActRII complex; plasma membrane; extracellular region; inhibin B complex; neuronal cell body; photoreceptor inner segment; photoreceptor outer segment
Genetic constraint (gnomAD): Loss-of-function variants: 9 observed, 22.9 expected, observed/expected ratio (o/e) 0.39, 90% interval 0.24 to 0.69. The upper end of that interval is the gene's LOEUF score, 0.69, which puts it in group 2 of 6, group 1 being the genes least tolerant of losing a copy. Missense variants: 436 observed, 481.26 expected, observed/expected ratio (o/e) 0.91, 90% interval 0.84 to 0.98. Synonymous variants: 231 observed, 214.52 expected, observed/expected ratio (o/e) 1.08, 90% interval 0.97 to 1.2.
Homologues: Orthologues: chimpanzee INHA (99% identical), macaque INHA (95% identical), pig INHA (84% identical), rabbit INHA (81% identical), dog INHA (80% identical), rat Inha (80% identical), mouse Inha (79% identical), guinea pig INHA (68% identical), tropical clawed frog inha (43% identical), zebrafish inha (33% identical). Paralogues in human: INHBE (20% identical), GDF10 (20% identical), BMP7 (20% identical), GDF6 (19% identical), GDF7 (19% identical), BMP5 (19% identical), BMP6 (19% identical), GDF5 (19% identical), GDF2 (19% identical), BMP2 (18% identical), BMP4 (18% identical), BMP8A (18% identical), and 19 more.
Diseases named in the same sentence as INHA in open-access papers:
INHA is named in the same sentence as 79 diseases in open-access papers, as found by Europe PMC text mining. Sharing a sentence is not in itself a finding about the gene and the disease. The quoted sentences say what the papers report.
tuberculosis (68 papers, 2009 to 2025). A chronic, recurrent infection caused by the bacterium Mycobacterium tuberculosis. "Here, we describe a TCR-based bispecific molecule that potently and selectively binds HLA-E in complex with a peptide encoded by the inhA gene of Mycobacterium tuberculosis (Mtb), the causative agent of tuberculosis in humans." (PMID 38691588, 2024). "In E. coli, for example, a synonymous mutation in the gene upstream of inhA, which encodes the target of isoniazid (used to treat tuberculosis), generates a new promoter and increases inhA expression by 3-4-fold." (PMID 30148850, 2018). "In an attempt to understand the molecular basis of first-line drug resistance in our setting, we sequenced the ropB, inhA, katG, pncA and embB genes associated with resistance to key drugs used in the treatment of DS tuberculosis." (PMID 27784282, 2016). "In an attempt to understand the distribution of drug resistance in our setting, we analysed the rpoB, katG, inhA, pncA and embB genes associated with resistance to key drugs used in the treatment of tuberculosis in clinical isolates of Mycobacterium tuberculosis in the KwaZulu-Natal province." (PMID 27784282, 2016). "The present study revealed the occurrence of TB as well as the detection of multidrug resistance associated with inhA and katG genes in patients with M. tuberculosis in upper Southern Thailand." (PMID 39077440, 2024). "This study investigated the occurrence of TB, antibiotic resistance due to inhA and katG gene mutations, and multidrug resistance in M. tuberculosis during fiscal years 2020–2022." (PMID 39077440, 2024). "This study aimed to investigate the occurrence and antibiotic resistance of TB caused by mutations in the inhA and katG genes in M. tuberculosis from patients in upper Southern Thailand (2020–2022)." (PMID 39077440, 2024). "The detection of mutation in inhA using rapid molecular tests such as LPA can help clinicians decide whether the patient will benefit from using high-dose INH or whether to prescribe ETH for the treatment of drug-resistant tuberculosis (DR‐TB)." (PMID 37153291, 2023). "Tryptanthrins are considered promising antituberculosis agents, active on both drug-susceptible and MDR-TB strains, with InhA predicted as their primary target." (PMID 33374765, 2020). "In addition, prior exposure to PTH may be associated with the increased frequency of INH-resistant tuberculosis strains with inhA mutations in China." (PMID 31382930, 2019). "We generated PCR products for five genes (rpoB, inhA, katG, gyrA and rrs) associatedwith drug resistance TB from MDR and XDR Mycobacterium tuberculosis (MTB) DNA samples." (PMID 30262979, 2018). "New coumarin-thiazolidinone and/or thiazole conjugates can treat tuberculosis (TB) by inhibiting the InhA enzyme." (PMID 40612619, 2025). "As a vital enzyme in mycolic acid biosynthesis and a central player in antimicrobial resistance, InhA remains a key target in tuberculosis drug discovery and research." (PMID 40901459, 2025). "InhA and KasA are regarded as the main targets of the well-known anti-tuberculosis drug isoniazid (INH)." (PMID 35444621, 2022). "Subsequently, from this model a new series of quinolinone-thiosemicarbazone 11a–e was designed and docked against two tuberculosis protein targets: enoyl-acyl carrier protein reductase (InhA) and decaprenylphosphoryl-β-D-ribose-2’-oxidase (DprE1)." (PMID 36671262, 2022). "AN12855, a recently developed diazaborine InhA inhibitor that binds to both the cofactor and substrate-binding unit of InhA, was effective in acute and chronic models of tuberculosis and was able to act upon INH-resistant M. tuberculosis strains." (PMID 35337063, 2022). "One of the most important targets is M. tuberculosis’ enoyl-acyl carrier protein reductase InhA which is considered a promising, well-studied target for anti-tuberculosis medication development." (PMID 35563096, 2022).
tuberculosis (continued). "The enoyl-acyl carrier protein reductase InhA of M. tuberculosis is one of the most crucial targets since it is a promising target that has undergone extensive research for anti-tuberculosis drug development." (PMID 35890098, 2022). "Genomes sequences of each isolate were screened for mutations in genes conferring resistance to first-line anti-tuberculosis drugs viz; rpsL, rrs, gidB for STR; KatG, inhA, ahpA, fab, ndh for INH; rpoA, rpoB, rpoC for RIF; embABC for EMB and pncA for PZA." (PMID 35205308, 2022). "The present study shows that the identified natural compound gravacridonediol possesses drug-like properties and also holds promise in inhibiting InhA, a key target enzyme of M.tb." (PMID 36009907, 2022). "Deletion of MSMEG_5634 also induced tolerance to triclosan (TRC), another anti-tuberculosis drug that targets InhA to block FAS-II and inhibits mycolic acid synthesis." (PMID 35444621, 2022). "enoyl-acyl carrier protein (ACP) reductase (InhA) is validated as a useful target for tuberculosis therapy and is considered an attractive enzyme to drug discovery." (PMID 36009907, 2022). "The strains evolved against the three first-line anti-TB drugs commonly harbored mutations associated with high-confidence drug resistance in M. tuberculosis, which comprised common mutations in inhA and katG in INZ-evolved strains, rpoB in RIF-evolved strains, and embABC in EMB evolved strains." (PMID 34302035, 2021). "InhA is a known target of isoniazid, a first-line anti-tuberculosis drug essential for the synthesis of mycolic acids." (PMID 33477495, 2021). "tuberculosis isolates in 49 countries (January 2000 to August 2013), are the katG (315 G/C) and the inhA (-15 C/T) promoter region." (PMID 32321155, 2020). "These efforts aim at developing an in vitro model to assay InhA activity that would serve as a surrogate of in vivo intracellular medium for anti-tuberculosis drug screening campaigns." (PMID 28754992, 2017). "This enzyme has been shown to be the primary target of isoniazid, a first-line anti-tuberculosis drug, thereby validating InhA as a target for anti-tuberculosis drug discovery." (PMID 28754992, 2017). "InhA, the target of tuberculosis drug isoniazid, was found to have low tractability despite having known ligands." (PMID 28714473, 2017). "174/183 (95.1%) patients had wild-type test results for inhA, katG and rpoB in the LPA assay indicating fully drug susceptible tuberculosis." (PMID 27333026, 2016). "Theobjective of this study was to develop a molecular platform to make a rapid diagnosisof multidrug-resistant (MDR) and extensively drug-resistant TB based on singlenucleotide polymorphism (SNP) mutations present in therpoB,katG, inhA,ahpC, andgyrA genes from Colombian M. tuberculosisisolates." (PMID 26841047, 2016). "Tuberculosis, a global threat to public health, is becoming untreatable due to widespread drug resistance to frontline drugs such as the InhA-inhibitor isoniazid." (PMID 22987724, 2012). "Triclosan analogues and di-phenyl ether compounds have been shown to inhibit InhA with nanomalar Ki and micromolar MICs and are both promising candidates as anti-tuberculosis compounds." (PMID 22987724, 2012). "We know that the enzyme InhA from M. tuberculosis is a highly flexible receptor and is a very important molecular target for the development of new drugs against tuberculosis." (PMID 22369213, 2011). "This constitutes, in our opinion, a strong basis to recommend the use of explicitly flexible models of Mtb’s InhA enzyme in virtual screening efforts to search for novel drug candidates against tuberculosis." (PMID 22369213, 2011). "Consequently, direct InhA inhibitors that bypass the need for activation by KatG are being developed to address multidrug-resistant tuberculosis." (PMID 40901459, 2025).
tuberculosis (continued). "Targeting fatty acid biosynthesis is a well-established antibacterial strategy: for example, the frontline tuberculosis drug isoniazid exerts its bactericidal activity by inhibiting the enoyl-ACP reductase InhA, a homologue of FabI, thereby blocking mycolic acid and fatty acid synthesis." (PMID 41463773, 2025). "INH is one of the first line anti-tuberculosis drugs, and its bactericidal mechanism is mainly through acting on its target enoyl acyl carrier protein reductase (InhA), and InhA is an enzyme involved mainly in fatty acid synthesis and mycolic acid biosynthesis." (PMID 37212713, 2023). "We therefore propose that anti-inhA PNA could improve therapy even when applied in minute doses as an addition to the current anti-tuberculosis drug regimen." (PMID 35171048, 2022). "For instance, anti-tuberculosis drugs isoniazid and ethionamide have been proven to inhibit the biosynthesis of mycolic acids and exert their function by inactivating the reductase activity of the enoyl-acyl-carrier protein (InhA)." (PMID 36547804, 2022). "Several essential enzymes involved in the biosynthesis of MAs (InhA, MmaA4, MmpL3, PacA, CmaA1, and CmaA2) that have been identified or may become potential targets of anti-tuberculosis drugs are highlighted." (PMID 36547804, 2022). "Factors which may have contributed to a favourable outcome in this cohort include, the majority of patients with INH monoresistance were new cases of tuberculosis and had low-level INH resistance causing mutations (in the inhA promoter; MIC range, 0.2–1 mg/L)." (PMID 28934422, 2017). "This makes InhA a prime target for the development of new anti-TB drugs, as compounds that can effectively inhibit this enzyme can potentially kill or prevent the growth of M. tuberculosis." (PMID 40388480, 2025). "For example, GSK-693 is a novel direct reversible InhA inhibitor of M. tuberculosis that binds to the active site and is currently being studied as a potential substitute for isoniazid in current TB treatment regimens." (PMID 35625207, 2022). "Scientists decided to utilize green tea along with triclosan in TB experiments; both compounds were used to target the InhA enzyme of tuberculosis." (PMID 32630150, 2020). "InhA plays and essential role in the biosynthesis of mycolic acids in M. tuberculosis and remains one of our primary and validated anti-TB drug targets." (PMID 28680153, 2017). "INH, an anti-tuberculosis pro-drug, needs to be activated by KatG to form a bactericidal molecule (IN-NAD+ adduct) and then target InhA." (PMID 36547804, 2022). "Being an anti-TB agent itself, ethambutol effectively targets and permeates the cell wall of M. tuberculosis, enabling an enhanced efficacy in combinatorial treatment with anti-inhA PNA." (PMID 35171048, 2022). "Therefore, the aim of this study was to describe mutations in rpoB, katG, inhA and ahpС genes and to select the dominating population of RIF and INH-resistant Mycobacterium tuberculosis strains in TB patients living in Kyrgyzstan." (PMID 29566660, 2018). "Owing to both the importance of this enzyme in M. tuberculosis physiology and as a “druggable” bona-fide target for the development of chemotherapeutic agents to treat tuberculosis (TB), evaluation of macromolecular effects on InhA mode of action was deemed worth pursuing." (PMID 28754992, 2017). "The combined results unambiguously indicate that pyridomycin is a competitive inhibitor of the NADH-binding site of InhA, NADH-dependent enoyl-[Acyl-Carrier-Protein] reductase, the target of the two anti-tuberculosis pro-drugs isoniazid and ethionamide." (PMID 22987724, 2012). "The enoyl-ACP reductase enzyme (InhA) from M. tuberculosis is recognized as the primary target of isoniazid (INH), a first-line antibiotic for tuberculosis treatment." (PMID 20428080, 2010).
preeclampsia (8 papers, 2012 to 2025). Preeclampsia is a hypertensive disorder of pregnancy that is characterized by new-onset hypertension with proteinuria presenting after 20 weeks of gestation, and depending on mild or severe forms may initially present with severe headache, visual disturbances, and hyperreflexia. "For example, genes involved in hormone regulation (i.e., CGB, CRH, INHA, and GH2), which have been previously shown to be key in the maintenance of pregnancy, show substantial overlap in preeclampsia studies." (PMID 26044726, 2015). "Interestingly and in accordance with the role of hypoxia in preeclampsia, HIF1A can regulate the expression of several top DEGs identified in the meta-analysis including: LEP, FLT1, INHA, BHLHE40, SPAG4, HK2, HILPDA and ERO1L." (PMID 27802351, 2016). "In accordance with the altered trophoblast pathophysiology in early-onset preeclampsia, many of the most differentially regulated genes in women with preeclampsia (LEP, CGB, LHB, INHA, SIGLEC6, PAPPA2, and FLT1) have predominant or unique expression in the syncytiotrophoblasts." (PMID 24991435, 2014). "Inhibin B (INHB), however, has not been studied, as well as INHA during preeclampsia or general pregnancy hypertension and only a previous study indicating significant differences in preeclampsia was found." (PMID 24219996, 2013). "FLT1, LEP, INHA and ENG genes were identified according to the literature, however, we also found other genes as FLNB, INHBA, NDRG1 and LYN highly significant but underexplored during normal pregnancy or preeclampsia." (PMID 24219996, 2013). "Supported by our data, activin A (INHBA) and inhibin A (INHA), but not inhibin B (INHB), are increased in patients with preeclampsia." (PMID 34970543, 2021).